GSK3B (glycogen synthase kinase 3 beta)
Diseases named in the same sentence as GSK3B in open-access papers (continued):
Sharing a sentence is not in itself a finding about the gene and the disease.
hepatocellular carcinoma (continued). "We recently demonstrated that GSK-3β inhibition triggered ASK1-JNK-dependent apoptosis in human hepatocellular carcinoma (HCC) cells." (PMID 29445085, 2018). "When treated with lithium, which is a GSK-3β inhibitor, hepatoma cells became resistant to etoposide and camptothecin." (PMID 27123999, 2016). "In a recent study, Wnt/β-catenin signaling was inhibited by PCDH20 through phosphorylation of GSK-3β in hepatocellular carcinoma." (PMID 27351130, 2016). "On the other hand, TGF-β inhibits GSK3β via ERK-MAPK in hepatocellular carcinoma and cultured peritoneal mesothelial cells, and GSK3 inhibition can lead to SMAD3 activation and fibrosis in cultured cardiac myocytes and fibroblasts." (PMID 26092126, 2015). "DHA supplementation also induced the formation of β-catenin/axin/GSK-3β complex and, hence, inhibited nuclear localization of β-cateninin hepatocellular carcinoma cell line." (PMID 24999478, 2014). "For the first time we found that GSK3β was involved in mtDNA depletion in response to TNF-α in hepatoma cells." (PMID 22911714, 2012). "Recent studies illuminated that MTDH can activate Wnt/β-catenin signaling pathway via ERK42/44 activation, which then leads to GSK3β phosphorylation, and thus facilitate nuclear translocation of β-catenin in hepatocellular carcinoma." (PMID 22768080, 2012). "In normal cells, Ser9GSK3β is dephosphorylated whereas in some hepatoma cells, GSK3β is constitutively phosphorylated on Ser9 by an up-regulated PI-3kinase/Akt signaling pathway." (PMID 22911714, 2012). "The inactivation of GSK-3β through S9 phosphorylation is involved in hepatitis B virus-x protein (HBX)-mediated β-catenin stabilization in hepatocellular carcinoma cells." (PMID 23049725, 2012). "Participation of Akt/GSK-3β/snail pathway in the EMT has also been reported previously in hepatocellular carcinoma line." (PMID 22315058, 2012). "Recently, the nonstructural 5A (NS5A) protein of HCV has been shown to inactivate GSK3β activity and subsequently increase accumulation of β-catenin in hepatoma cells." (PMID 22110662, 2011). "For instance, HBx has been reported to be essential for the activation of Wnt/b-catenin signalling in hepatoma cells, and reduced the phosphorylation level of b-catenin by suppressing GSK-3b function through the Erk pathway." (PMID 19402906, 2009). "On the contrary, recent studies with hepatoma cells have shown that imatinib attenuates insulin-induced phosphorylation of Akt and glycogen synthase kinase-3β (GSK-3β)." (PMID 19693287, 2009). "Similarly, circLIFR has been identified as a tumor suppressor in hepatocellular carcinoma by modulating the miR-624-5p and GSK-3β/β-catenin signaling pathway." (PMID 38914806, 2024). "The survival analysis results indicated that a higher expression level of GSK3B in hepatocellular carcinoma patients could predict lower survival probability." (PMID 38814517, 2024). "Furthermore, SangerBox online analysis of the TCGA-LIHC database revealed that GSK3B was notably upregulated in hepatocellular carcinoma tissues." (PMID 38814517, 2024). "In addition, GSK3B expression was found to be upregulated in hepatocellular carcinoma tissues in GSE112790 dataset." (PMID 38814517, 2024). "GSK3β is involved in canonical signalling pathways and cancer progression as a tumor suppressor; however, it also functions as an oncogene to accelerate tumor growth in pancreatic and colorectal cancer and hepatocellular carcinoma." (PMID 39218913, 2024). "GSK3B demonstrated a significantly elevated expression in patients with hepatocellular carcinoma, which could predict hepatocellular carcinoma patients’ impaired prognosis based on GEO dataset and TCGA database." (PMID 38814517, 2024).
hepatocellular carcinoma (continued). "Upon endoplasmic reticulum stress, amplified FGF19 promotes tumor cell proliferation through activating fibroblast growth factor (FGF) receptor 4 (FGFR4)-glycogen synthase kinase-3beta (GSK3β)-nuclear factor erythroid-2-related factor-2 (Nrf2) signaling in hepatocellular carcinoma." (PMID 36751636, 2023). "To illustrate, cisplatin-resistant non-small cell lung cancer (NSCLC) cell line showed upregulation of β-catenin due to phosphorylation-dependent inhibition of GSK3β, and cisplatin-resistant hepatocellular carcinoma cells exhibited nuclear accumulation of GSK3β." (PMID 36733702, 2023). "Additionally in GC and in hepatocellular carcinoma, Gal-3 activates GSK-3β, β-catenin, and the Insulin-like growth factor-binding protein 3; resulting in angiogenesis and EMT." (PMID 38022609, 2023). "MiR-3677-3p promotes hepatocellular carcinoma progression by inhibiting GSK3β." (PMID 36090902, 2022). "Previous studies found the interaction between MYH9 and GSK3-β in hepatocellular carcinoma and nasopharyngeal carcinoma, and GSK3-β could induce the degradation of β-catenin." (PMID 34743203, 2022). "Furthermore, AKT/GSK-3β/Snail signaling is involved in the migration and invasion of hepatocellular carcinoma cells." (PMID 35327583, 2022). "It was reported that MTH9 could blocked GSK3β ubiquitination so as to upregulate β‐catenin level and finally drive aggressive behaviour in hepatocellular carcinoma." (PMID 33755268, 2021). "Likewise, another study on hepatocellular carcinoma has revealed that an MYH9/GSK3β/β-catenin/c-Jun regulatory circuit improves cancer stemness, migration, invasion, and resistance to sorafenib." (PMID 34425650, 2021). "LncRNA RUNX1-IT1 can promote the expression of Glycogen Synthase Kinase 3 Beta (GSK3B) by competitively binding miR632, thereby inactivating the Wnt/β-catenin pathway of hepatoma cells to inhibit the proliferation, migration, and differentiation of cancer stem cells." (PMID 34758879, 2021). "Interestingly, a preceding study has uncovered that FSTL1 aggravates hepatocellular carcinoma progression via inducing AKT/GSK-3β pathway activation." (PMID 34555811, 2021). "However, the expression and function of GSK-3β in hepatocellular carcinoma (HCC) remain largely unexplored." (PMID 31938062, 2020). "In addition, GSK-3β activities that are required for N-terminus hyperphosphorylation-mediated degradation of β-catenin are downregulated due to increased GSK-3β-Ser9 phosphorylation in DCLK1-overexpressing hepatoma cells." (PMID 32601309, 2020). "Gsk3β has been reported to be regulated by ASPH inhibitor in hepatocellular carcinoma." (PMID 33015050, 2020). "DCLK1 overexpression in hepatoma cells also increased phosphorylation of GSK-3β at Ser9." (PMID 32601309, 2020). "In hepatocellular carcinoma, GSK3B increases miR-122 levels and activates miR-181 expression." (PMID 31801236, 2019). "In order to determine whether this regulation of GSK3β is also present in other cancer cells, we determined the changes in GSK3β levels in hepatocellular carcinoma cells (Huh7) and pancreatic cancer cells (BXPC3)." (PMID 27602497, 2016). "Further studies demonstrated that bufalin, one compound in Chansu, induced apoptosis of gastric cancer cells by inhibition of AKT signaling pathway and inhibiting proliferation of hepatocellular carcinoma cells through inhibiting AKT/GSK3β/β-catenin/E-cadherin signaling pathway." (PMID 25256890, 2014). "The BCAA direct effect may be the induction of hepatocellular carcinoma apoptosis and the inhibition of hepatocellular carcinoma cells to inhibit the phosphorylation of GSK3β." (PMID 24663086, 2014). "Thus, our data suggested the Akt/GSK-3β/cyclin D1 signaling pathway mediated the function of βKlotho in hepatoma cells proliferation and hepatocarcinogenesis." (PMID 23383245, 2013).
hepatocellular carcinoma (continued). "Additionally, core protein increases and stabilizes β-catenin levels in hepatoma cell line Huh7 through inactivation of GSK-3β, which contributes to the up-regulation of downstream target genes, such as c-Myc, cyclin D1, WISP2 and CTGF." (PMID 22110662, 2011). "However, the precise mechanism by which β-Sitosterol exerts it effects on hepatocellular carcinoma through modulation of GSK3B remains unclear." (PMID 38814517, 2024). "Compared with nontumor tissues, FAM134B is upregulated in hepatocellular carcinoma (HCC), as well as being associated with tumor proliferation and metastasis via the AKT and GSK3-β signaling pathways." (PMID 35327508, 2022). "Also, MYH9 could bind with and degrade GSK3β through ubiquitin, therefore β-catenin was downregulated to induce the epithelial-mesenchymal transition in hepatocellular carcinoma." (PMID 35369347, 2022). "It has been observed that the MAEL has a critical function during hepatocellular carcinoma (HCC) progression through AKT/GSK3b/SNAILl signaling." (PMID 33902648, 2021). "Experiments on hepatocellular carcinoma SK-HEP-1 and HCCLM3 cells did show that the activation of CXCR6 causes a reduction in p38 MAPK activation and thus the activation of glycogen synthase kinase 3β (GSK3β), which leads to a reduction in the amount of β-catenin in the plasma membrane." (PMID 33800554, 2021). "A study showed that knockdown of SNHG5 remarkably inhibited GSK3β and the Wnt/β-catenin pathway in hepatocellular carcinoma (HCC) or brain glioma cell lines." (PMID 33176855, 2020). "During obesity-associated hepatocellular carcinoma (HCC) development, expression of interleukin-6 (IL-6), which results from a chronic low-grade proinflammatory state in white adipose tissue and liver, helps to stabilize Mcl-1 via promotion of GSK3β inactivation and suppression of HUWE1." (PMID 30176860, 2018). "Dachshund inactivates Wnt signaling and inhibits hepatocellular carcinoma (HCC) growth through decreasing GSK3β Ser9 phosphorylation." (PMID 28430641, 2017). "Furthermore, it has been suggested that persistent phosphorylation of GSK-3β may have a fundamental impact on glycogen metabolism and cell growth in hepatoma cells." (PMID 29379583, 2017). "This novel β-catenin isoform promotes hepatocellular carcinoma (HCC) proliferation and metastasis by antagonizing GSK3β (glycogen synthase kinase 3 beta)-induced β-catenin phosphorylation and degradation, stabilizing full-length β-catenin, and activating the Wnt pathway." (PMID 40034125, 2025). "GSK3B inhibitor (CHIR-98014) notably inhibited cell proliferation and invasion, promoted cell apoptosis and cell cycle arrest at G0/G1 phase in in hepatocellular carcinoma cells." (PMID 38814517, 2024). "GSK3B inhibitor (CHIR-98014) notably inhibited cell proliferation and invasion, promoted cell apoptosis and cell cycle arrest at G0/G1 phase in hepatocellular carcinoma cells." (PMID 38814517, 2024). "Yet other mechanisms that mediate the activity of NDRG1 have been reported examining Huh7 and HepG2 hepatocellular carcinoma cells, where direct binding of NDRG1 to GSK-3β prevented its binding to β-catenin." (PMID 38815861, 2024). "DHA induces the dephosphorylation of GSK-3β, which results in the downregulation of β-catenin and TCF/LEF, and eventually, in the reduction in cell growth in hepatocellular carcinoma cells." (PMID 36675245, 2023). "In hepatocellular carcinoma, copper with disulfiram inhibits T-cell infiltration by inhibiting PARP1 activity and enhancing GSK3β Ser9 site phosphorylation, which in turn upregulates PD-L1 expression." (PMID 37822927, 2023). "WEE2-AS1 contributes to the proliferation, migration, and invasion of hepatocellular carcinoma cells via regulating the fermitin family member 3 pathway and activating the PI3K/AKT/GSK3b signaling pathway." (PMID 36747161, 2023).
hepatocellular carcinoma (continued). "In hepatocellular carcinoma, EPHB2 enhances cancer stem cell properties and drive sorafenib resistance by activating SRC/AKT/GSK3β/β-catenin signaling cascade." (PMID 36032135, 2022). "For example, a lectin from Bandeiraea simplicifolia seeds (BS-I) inhibited cancer cells, hepatocellular carcinoma, invasion, and migration, mediated by inhibiting the activation of the AKT/GSK-3β/β-catenin pathway." (PMID 36547923, 2022). "In hepatocellular carcinoma, galectin-3 overexpression enhanced metastasis through the PI3K/AKT/GSK-3β/β-catenin signaling cascade." (PMID 34035807, 2021). "MiR-455 inhibits the EMT process in pancreatic cancer and hepatocellular carcinoma by modulating the Wnt/β-catenin and STK17B/AKT/GSK-3β/Snail signaling, respectively." (PMID 34174908, 2021). "In hepatocellular carcinoma, knockdown of lncRNA IHS reduced the level of phosphorylated GSK-3β, which greatly inhibited the activity of AKT/GSK-3β signaling pathway, and promoted the proliferation and metastasis of tumors." (PMID 34485505, 2021). "Moreover, GSK-3β regulates mTOR activity as well as in cancer research in hepatocellular carcinoma (HCC)." (PMID 35095838, 2021). "In hepatocellular carcinoma (HCC), transfection with an ILK expression vector was able to recover the decreased expression of its downstream genes AKT and GSK3β phosphorylation, and affected cell proliferation and apoptosis." (PMID 33531984, 2021). "In hepatocellular carcinoma, CTHRC1 downregulates miR-155-5p through the activation of GSK-3β-involved Wnt/β-catenin signaling to promote tumor formation." (PMID 32848510, 2020). "The transcription factor Slug is the CD147 upstream mediator in epithelial-mesenchymal transition during hepatocellular carcinoma progression, the signaling cascade of which is TGF-β/PI3K/Akt/GSK3β/Snail/Slug/CD147." (PMID 33490072, 2020). "β-Catenin regulation by GSK-3β has been shown to play a key role in hepatocellular carcinoma (HCC)." (PMID 29379583, 2017). "On the other hand, GSK-3β activation with LY294002 and with exogenous expression of Ser9 GSK-3β sensitizes hepatoma cells to apoptosis induced by those drugs." (PMID 27123999, 2016). "In hepatocellular carcinoma (HCC), we previously reported that SIRT3 induced cell apoptosis by regulating GSK-3β/Bax signaling pathway." (PMID 27367026, 2016). "In contrast, GSK-3β did not correlate with Cyclin D1 expression in hepatocellular carcinoma cells and fibroblasts." (PMID 39241034, 2024). "In summary, our findings suggest that upregulation of endogenous or exogenous of GSK3B can counteract some but not all inhibitory effects exerted by β-Sitosterol on hepatocellular carcinoma cells." (PMID 38814517, 2024). "Furthermore, another study has shown that DSF-Cu combination can impede GSK3β activity via the inhibition of PARP1, resulting in immunosuppression via PD-L1 stabilization in hepatocellular carcinoma." (PMID 37259318, 2023). "These bromobenzofuran-oxadiazole structural hybrids BF1-9 were evaluated in vitro against anti-hepatocellular cancer (HepG2) cell line as well as for their in silico therapeutic potential against six key cancer targets, such as EGFR, PI3K, mTOR, GSK-3β, AKT, and Tubulin polymerization enzymes." (PMID 36769327, 2023). "In hepatoma and hepatic cells, HBx expression has been shown to promote epithelial-mesenchymal/AKT/transmission and activate the snail protein via activating the PI3K/AKT/GSK-3b signal pathway, which aids EMT and the spread of hepatoma attack in vivo and in vitro." (PMID 38144298, 2023). "The stability of Snail can be modulated by the AKT/GSK-3β signaling pathway, and activation of this pathway may further drive EMT in hepatoma and ovarian carcinoma cells." (PMID 35327583, 2022). "In hepatocellular carcinoma, PIGR-loaded extracellular vesicles could activate Akt/GSK3β/β-catenin signaling cascades, driving cancer stemness, tumorigenesis, and metastasis." (PMID 36157233, 2022).
hepatocellular carcinoma (continued). "Furthermore, the CXCL16→CXCR6 axis reduces p38 MAPK activity in hepatocellular carcinoma SK-HEP-1 and HCCLM3 cells, which leads to the activation of GSK3β and consequently, to a decreased amount of β-catenin in the plasma membrane." (PMID 33800554, 2021). "In hepatocellular carcinoma, miR-346 promotes cell proliferation, migration and invasion by targeting KFL14, and in renal carcinoma, miR-346 promotes cell growth by targeting GSK-3β." (PMID 31807116, 2019). "With regard to the role of bufalin in hepatocellular carcinoma, two studies have shown that inhibition of AKT/GSK3β/β-catenin/E-cadherin signaling pathway may be involved in its antimetastatic property." (PMID 26958938, 2016). "Phosphorylation of GSK3β at threonine 43 by Erk (extracellular-signal-regulated kinase), primes GSK3β for phosphorylation at Ser9 by p90RSK, and mediates HBV-X protein (HBX)-induced upregulates β-catenin in human hepatocellular carcinoma cells." (PMID 24594309, 2014). "A reduction in GSK3β Ser9 phosphorylation and decrease in β-catenin levels as well as EMT-related Wnt target genes in response to the compound were found in a separate study in HepG2 hepatocellular carcinoma and in A2780 and SK-OV-3 epithelial ovarian cancer lines, inhibiting EMT in these lines." (PMID 40427472, 2025). "MYH9 can also interact with GSK3β and facilitate GSK3β ubiquitination and degradation to favor cancer stemness properties in hepatocellular carcinoma, illustrating that KRT19/MYH9 may coordinate cell fate specification via orchestrating regulatory hubs with GSK3β." (PMID 41345704, 2025). "Moreover, AP4 regulates LAPTM4B, and activates the PI3K/AKT signaling pathway and glycogen synthase kinase 3 beta (GSK3b), leading to c-myc accumulation, which amplified the effect of the PI3K/AKT pathway on the drug resistance of hepatocellular carcinoma cells." (PMID 40231269, 2025). "Recent in vitro and in vivo studies in hepatocellular carcinoma models have demonstrated that the slow-releasing H2S donor GYY4137 significantly inhibits the phosphorylation of GSK-3β and β-catenin, thereby downregulating the AKT/GSK-3β/β-catenin pathway and promoting apoptosis in tumor cells." (PMID 41226825, 2025). "For example, disulfiram–Cu enhances PD-L1 levels in hepatocellular carcinoma (HCC) cells by inhibiting PARP1 and promoting GSK-3β phosphorylation, which reduces T-cell infiltration." (PMID 39867656, 2024). "This aligns with the finding that silencing CLU gene transcription decreases the phosphorylation level of AKT and GSK-3β, subsequently inhibiting the proliferation of HCCLM3 cells in hepatocellular carcinoma (HCC)." (PMID 38667280, 2024). "The relationship between exercise and angiogenesis is also supported in mice bearing hepatocellular carcinoma where the swimming intervention impaired hypoxia through the inhibition of HIF-1α and serine/threonine kinase 1 (AKT)/Glycogen synthase kinase 3 beta (GSK-3β)/β-CATENIN signaling pathways." (PMID 39555455, 2024). "It has been well-established that overexpression of STK17B has closely associated with the tumorigenesis of hepatocellular carcinoma (HCC) and breast cancer, and inhibition of STK17B inhibited HCC tumorigenesis and metastasis via AKT/GSK3β/Snail signaling." (PMID 35889528, 2022). "Linc00941 (also known as lncRNA-MUF) was recently described as EMT-promoter in hepatocellular carcinoma cells, where it exerts a double function, it sponges miR-34a, leading to SNAIL1 upregulation and binds Annexin2 (ANXA2) and Glycogen synthase kinase 3 beta (GSK3β)." (PMID 31003545, 2019). "In addition, the expression level of glycogen synthase kinase 3 beta (GSK3B) within the Cancer Genome Atlas-Liver Hepatocellular Carcinoma (TCGA-LIHC) database was analyzed, along with its correlation to the survival outcomes of patients with hepatocellular carcinoma." (PMID 38814517, 2024).